SIRT3 (sirtuin 3)
Diseases named in the same sentence as SIRT3 in open-access papers (continued):
Sharing a sentence is not in itself a finding about the gene and the disease.
renal fibrosis (continued). "Additionally, another study revealed that reduced SIRT3 expression is correlated with elevated acetylation in mitochondrial tubular cells during the early stages of renal fibrosis." (PMID 39911234, 2024). "Thus, our data clearly demonstrate that anti-inflammatory effects against Diosmin-induced renal fibrosis can be promoted by regulating SIRT3-mediated nuclear NF-κB p65 expression." (PMID 38195573, 2024). "In contrast, activation of Sirt3 improved their acetylation levels and delayed renal fibrosis." (PMID 38347622, 2024). "Moreover, a loss of SIRT3 also causes a transformation from pericytes to fibroblasts by enhancing collagen I and TGF-β1 expression, making them susceptible to Ang II-induced renal fibrosis." (PMID 37237500, 2023). "The deacetylation of PDHE1α by SIRT3 at lysine 385 can prevent renal fibrosis." (PMID 37196115, 2023). "Based on these studies, SIRT3 is reduced in renal fibrosis and may impair the CPT1a activity due to becoming acetylated." (PMID 37064892, 2023). "Notably, PAA exerted the inhibitory effect on renal fibroblast activation and interstitial fibrosis in a Sirt3-dependent manner, and Sirt3 was required for PAA, highlighting Sirt3 functioned as a promising therapeutic target for renal fibrosis." (PMID 36470978, 2023). "SIRT3 has long been an important molecular target against renal fibrosis." (PMID 35560773, 2022). "This suggests that the restoration of SIRT3 may be an effective strategy for combatting diabetes-related renal fibrosis by inhibiting abnormal glycolysis." (PMID 36142794, 2022). "Sirt3 knockout in mice resulted in increased levels of EndoMT and reactive oxygen species (ROS), and promoted renal dysfunction, while in Sirt3 knock-in EC-specific transgenic mice, renal fibrosis and EndoMT, as well as oxidative stress, were ameliorated." (PMID 36408221, 2022). "Interestingly, the function of over expression of LSD1 on renal fibrosis biomarkers was partially counteracted by overexpression of SIRT3." (PMID 34983623, 2022). "The activation of SIRT3 by honokiol ameliorated acetylation and prevented renal fibrosis." (PMID 34518519, 2021). "In addition, SIRT3 activators, like honokiol, alleviate renal fibrosis in mice with unilateral ureter obstruction." (PMID 34899370, 2021). "Because SIRT3 overexpression could rescue tubule damage and ameliorate renal fibrosis, we believe that reducing SIRT3 and increasing mitochondrial protein acetylation is a novel mechanism of tubular disturbance in the development of renal fibrosis." (PMID 34518519, 2021). "Our current work focuses on the role of Sirt3 activation in UUO-induced renal fibrosis." (PMID 31936371, 2020). "In conclusion, activation of SIRT3 by HKL treatment might have a beneficial effect on UUO-induced renal fibrosis through SIRT3-dependent regulation of mitochondrial dynamics and the NF-κB/TGF-β1/Smad signaling pathway." (PMID 31936371, 2020). "To address changes in mitochondrial dynamics in UUO-induced renal fibrosis, we evaluated the expression of mitochondrial Sirt3 and mitochondrial dynamin-related protein 1 (DRP1) and optic atrophy 1 (OPA1) expression after ureteral obstruction with vehicle or HKL treatment." (PMID 31936371, 2020). "SIRT3 knockout mice exhibited more severe renal fibrosis after Ang-II infusion." (PMID 33233553, 2020). "In conclusion, activation of SIRT3 via HKL treatment might have beneficial effects on UUO-induced renal fibrosis through SIRT3-dependent regulation of mitochondrial dynamics and the NF-κB/TGF-β1/Smad signaling pathway." (PMID 31936371, 2020). "The expression of TGF-β1, which plays an important role in renal fibrosis, could also be inhibited by dioscin via Sirt3 to mitigate renal fibrosis." (PMID 31511824, 2019). "Moreover, SIRT3 ablation aggravated renal function impairment and renal fibrosis in hypertensive nephropathy." (PMID 28465484, 2017).
renal fibrosis (continued). "Therefore, our data suggest that SIRT3 may be a potential therapeutic target of inflammation-related diseases such as renal fibrosis." (PMID 38195573, 2024). "In addition, SIRT3 overexpression reduced the expression of NF-κB p65, suggesting that SIRT3 mediates the regulation of TGF-β1-induced inflammation mainly by regulating the expression of NF-κB p65 during renal fibrosis, data which are consistent with the results of other reports." (PMID 38195573, 2024). "LSD1 may induce renal fibrosis not only through SIRT3 but also other genes." (PMID 34983623, 2022). "Thus, restoration of SIRT3 expression or pharmacological activation of SIRT3 may mitigate renal fibrosis in diabetic conditions." (PMID 34071497, 2021). "We then investigated whether SIRT3 activation correlates with tubular damage and renal fibrosis." (PMID 34518519, 2021). "Interestingly, Ang-II infusion caused an iron overload in the mouse kidneys, and knockout of SIRT3 further promoted iron overload, which might also contribute to the exacerbation of renal fibrosis." (PMID 33233553, 2020). "Altogether, SIRT3 may protect against renal fibrosis in hypertensive nephropathy." (PMID 28465484, 2017). "SIRT3 knockout exacerbated renal fibrosis in young mice subjected to UUO, whereas SIRT3 overexpression attenuated fibrosis in aged UUO mice." (PMID 40698425, 2025). "Activation of SIRT3 has been shown to restore FAO function in tubular epithelial cells and prevent renal fibrosis through the deacetylation of pyruvate dehydrogenase E1α." (PMID 39911234, 2024). "Although the critical function of Sirt3 in the renal aging process through the Ang II-AT1R signaling pathway remains controversial, Sirt3−/− mice develop more serious renal fibrosis than their age matched wild-type (WT) littermate controls as they age." (PMID 35627181, 2022). "The metabolic profile of renal TECs during the development of renal fibrosis switches from OXPHOS to glycolysis, which is relevant to SIRT3 expression and activity." (PMID 34518519, 2021). "SGLT2 inhibitors can also help to restore function to SIRT3, a mitochondrial NAD+-dependent deacetylase that can inhibit epithelial–mesenchymal transition (EMT) and renal fibrosis, and which is suppressed by high glucose levels." (PMID 34769288, 2021). "The proteins expressions of renal fibrosis, quinolinate phosphoribosyltransferase (QPRT), sirtuin 3 (SIRT3), and mitochondrial dynamics were determined and quantified by Western blot analysis." (PMID 34938344, 2021). "Lin and colleagues demonstrated that FOXO3a, mediated by Sirt3, suppresses the EMT in renal fibrosis vascular pathology." (PMID 34122724, 2021). "The deacetylation of PDHE1α by SIRT3 provides the primary link between glycolysis and the TCA cycle in TECs during the development of renal fibrosis." (PMID 34518519, 2021). "We analyzed SIRT3 expression in kidney biopsy specimens from 14 patients with CKD and various degrees of renal fibrosis using quantitative real-time polymerase chain reaction (qRT-PCR)." (PMID 34518519, 2021). "In renal disease, Honokiol stimulates SIRT3 activity to block the NF-κB-TGF- β1/Smad regulated inflammation and fibrosis signaling in renal fibrosis mice model." (PMID 32724473, 2020). "In our study, we found that SIRT3 absence does not directly worsen renal fibrosis but significantly diminishes the therapeutic effect of JT." (PMID 40144655, 2025). "The lack of improvement in renal fibrosis with high-dose JT in SIRT3−/− mice further confirms SIRT3’s central role in JT’s therapeutic mechanism." (PMID 40144655, 2025). "In addition, dioscin markedly upregulates sirtuin-3 (Sirt3) levels to regulate TGF-β1/Smad signaling, and it exerts an inhibitory effect on renal fibrosis." (PMID 39465434, 2024).
renal fibrosis (continued). "Sirt3 significantly decreased in fibrotic kidneys from UUO models and patients with renal fibrosis." (PMID 36470978, 2023). "LSD1 deficiency leads to alleviate STZ-induced renal injury and overexpression of LSD1 induces renal fibrosis via decreasing SIRT3 expression and activating TGF-β1/Smad3 pathway, which provides a reasonable strategy for developing novel drugs targeting LDS1 to block renal fibrosis." (PMID 34983623, 2022). "Given the roles of TGF-β1/Smad3 pathway and SIRT3 in renal fibrosis, we hypothesized that LSD1 might play a vital role in DN-induced renal fibrosis through regulating SIRT3." (PMID 34983623, 2022). "Therefore, the up regulation of SIRT1, SIRT3 and SIRT4 and downregulation of Claudin 1 by MR extract might prevent renal fibrosis by suppressing mitochondrial oxidative stress and the production of inflammatory cytokines." (PMID 35956936, 2022). "According to previous studies, SIRT1 and SIRT3 (both decreased in TGF-β-induced EndMT) seem to be TGF-β inhibiting factors, so their upregulation could be a chance to attenuate both cardiac and renal fibrosis, thus mitigating cardio-renal syndromes, in which fibrosis plays an important role." (PMID 40218970, 2025).
hepatocellular carcinoma (48 papers, 2012 to 2026). A malignant tumor that arises from hepatocytes. "In another study where hepatocellular carcinoma cells were infected with lentivirus overexpressing SIRT3, it was shown that SIRT3 overexpression significantly enhanced cellular susceptibility to three chemotherapeutic agents." (PMID 37345199, 2023). "Some studies indicated that decreased expression of SIRT3 was associated with poor prognosis in pancreatic, gastric, and hepatocellular cancer." (PMID 31113446, 2019). "Additionally, low SIRT3 expression in hepatocellular carcinoma tissues has been associated with advanced disease and poorer prognosis, with an inverse relationship between SIRT3 levels and lactylation." (PMID 39325940, 2024). "Furthermore, in the 4 studies with pathological differentiation data in hepatocellular carcinoma patients, a significant association was found between SIRT3 expression and pathological differentiation (OR = 0.69, 95% CI = 0.48–0.98, P = 0.04)." (PMID 27483432, 2016). "SIRT3 protein expression in hepatocellular carcinoma (HCC) is associated with the degree of differentiation, pathological features, and complications with portal vein tumor thrombus." (PMID 27686535, 2017). "SIRT3 is underexpressed in hepatocellular carcinoma (HCC) and can delactylate lysine 348 lactylation of CCNE2 to prohibit HCC growth." (PMID 40777993, 2025). "In hepatocellular carcinoma, SIRT3 reduction promotes cyclin E2 lactylation, enhancing the proliferation and invasion of hepatocellular carcinoma cells." (PMID 40994548, 2025). "SIRT3, a lactylation eraser, induces apoptosis in hepatocellular carcinoma by inhibiting cyclin E2 lactylation." (PMID 40994548, 2025). "In HBV-related hepatocellular carcinoma, the expression of the lactylation eraser SIRT3 was substantially lower in tumor tissues and was negatively correlated with the tumor stage." (PMID 40994548, 2025). "Associations of SIRT3 and SIRT4 were in agreement with earlier reports about their effects on tumour suppression and on improved patient outcomes in hepatocellular carcinoma, and they are consistent with associations of higher SIRT3 expression levels with drug sensitivity in HCC cell lines." (PMID 38369747, 2024). "SIRT3-mediated delactylation of cyclin E2 (CCNE2) curbs hepatocellular carcinoma cell growth by inducing apoptosis." (PMID 38773972, 2024). "In hepatocellular carcinoma, SIRT3 can enhance apoptosis by overexpressing caspase 9 cleavage and depleting SIRT3 in cancer cells." (PMID 39062982, 2024). "Consistent with the previous findings in hepatocellular carcinoma cells, these data demonstrated that SIRT3 is capable of being SUMOylated at Lys288 in AML cells." (PMID 35955415, 2022). "In hepatocellular carcinoma, the miR-494 induces endothelial to mesenchymal transition (EndMT) to promote cancer metastasis by targeting the SIRT3 signaling pathway." (PMID 35832551, 2022). "Knockdown of SIRT3 in human hepatoma cells confirmed the upregulation in both HIF-1α and LIPIN 1 protein levels, whereas this increase was blunted when cells were exposed to palmitate." (PMID 32912335, 2020). "Studies were conducted in wild-type (WT) and Sirt3−/− mice fed a standard diet or a HFD and in SIRT3-knockdown human Huh-7 hepatoma cells." (PMID 32912335, 2020). "The increase in CD36 was confirmed in cultured human hepatoma cells, where either SIRT3 inhibition or knockdown in the presence of palmitate raised both CD36 and NQO1." (PMID 32912335, 2020). "SIRT3 can also inhibit growth and proliferation of the human hepatoma cells HepG2 and induce apoptosis and is a tumor suppressor in the human hepatoma cells Huh7, reducing phosphorylation of PI3K/Akt." (PMID 31623280, 2019). "MiR-494 suppressed SIRT3 expression, additionally enhanced expression of mesenchymal cell markers, while exerted effects on cell proliferation and migration of hepatoma cell lines." (PMID 31076630, 2019).
hepatocellular carcinoma (continued). "The SIRT3 mechanism should thus be related to ROS levels in the mitochondria; however, low SIRT3 expression was reported to act as a poor independent prognostic factor of survival in patients with postsurgical hepatocellular carcinoma." (PMID 27686535, 2017). "In hepatocellular carcinoma cells, overexpression of SIRT3 facilitated the activation of the JNK signaling pathway, resulting in apoptosis; however, low SIRT3 expression is associated with a markedly shorter period of clinical recurrence." (PMID 27686535, 2017). "SIRT3 functions as a tumor suppressor in a variety of cancers including B cell malignancies, prostate cancer and hepatocellular carcinoma." (PMID 28423723, 2017). "Resveratrol is also a SIRT3 activator that has been suggested to be the therapeutic potential for cancer prevention in neuroblastoma, hepatoma, breast, lung, pancreatic, and prostate cancers." (PMID 28600541, 2017). "It is known that relative SIRT3 protein expression gradually decreases with the increases in differentiation between hepatoma cells and between the deterioration and progression of hepatocellular cells." (PMID 27686535, 2017). "Univariate analysis of SIRT3 expression and clinicopathologic variables in 248 patients with primary hepatocellular carcinoma (log-rank test)." (PMID 23272146, 2012). "Moreover, SIRT3 expression is downregulated in high glycolytic and proliferative hepatocellular carcinoma cells of human patients, xenograft models, and cell lines, showing a correlation between this protein and cancer." (PMID 37345199, 2023). "The underexpression of sirtuin 3 in hepatocellular carcinoma promotes the lactylation of cyclin E2, which in turn promotes tumor progression, and sirtuin 3 is a potential therapeutic target for hepatocellular carcinoma." (PMID 37675097, 2023). "In subgroup analyses, patients with lower SIRT3 expression correlate with poor differentiation as compared with those with higher SIRT3 expression in hepatocellular carcinoma (OR = 0.69, 95% CI = 0.48–0.98, P = 0.04) and gastric cancer (OR = 0.33, 95% CI = 0.21–0.50, P<0.00001)." (PMID 27483432, 2016). "Furthermore, treatment of HepG2 hepatoma cells with 3 mM metformin impaired ATP synthesis, while overexpression of SIRT3 increased ATP content in a dose-dependent manner and partially counteracted metformin effect." (PMID 23166782, 2012). "In hepatocellular carcinoma (HCC), we previously reported that SIRT3 induced cell apoptosis by regulating GSK-3β/Bax signaling pathway." (PMID 27367026, 2016). "It has been reported that excessive mitochondrial Ca2+ influx inhibited NAD+-dependent deacetylase activity of SIRT3, followed by a decrease in SOD2 activity, which contributes to aberrant ROS production and metastasis of hepatocellular carcinoma." (PMID 40166941, 2025). "A few miRNAs (n = 17) are known to be upregulated in hepatocellular carcinoma, of which miR-494 targets the SIRT3 and TGF-β/SMAD signaling pathways to promote cell proliferation and migration of hepatoma cells." (PMID 35954293, 2022). "SIRT3 is a member of the Sirtuin family of class III histone deacetylases and is also considered a tumor suppressor in some solid tumors like hepatocellular carcinoma." (PMID 35392973, 2022). "While SIRT3 was found to be a novel regulator of cardiovascular disease, and PARP6 has suggested inhibiting the development of hepatocellular carcinoma and intestinal cancer." (PMID 36439178, 2022). "SIRT3 expression and its significance in hepatocellular carcinoma (HCC) remain largely unclear." (PMID 23272146, 2012). "It indicated that miR-494 could straight control mRNA and the protein expression levels of SIRT3, further affect expression level of TGF-β protein in hepatoma cell lines." (PMID 31076630, 2019).
hepatocellular carcinoma (continued). "Here, we report that in hepatocellular carcinoma (HCC) cells under glucose-deprived conditions, SCIC2.1 treatment induced overexpression of SIRT1, SIRT3, and SIRT6, modulating metabolic response." (PMID 37715252, 2023). "Additionally, there have been a few studies on SIRT3/HIF-1α pathway in cervical cancer and hepatocellular cancer but not in DTC." (PMID 35136826, 2022). "Moreover, SIRT3 has nonhistone delactylase activity, removing lactylation from the K348la site of cyclin E2 (CCNE2) in hepatocellular carcinoma (HCC) cells." (PMID 40655145, 2025).